ENSG00000252537
Gene: Small nucleolar RNA gene on chromosome 10 (16,005,808 to 16,005,923, forward strand). Ensembl gene ENSG00000252537.
Homologues: Orthologues: rat LOC120102627 (66% identical). Paralogues in human: SNORA31B (72% identical), SNORA31 (59% identical).